PER1 (period circadian regulator 1)
Diseases named in the same sentence as PER1 in open-access papers (continued):
Sharing a sentence is not in itself a finding about the gene and the disease.
tumor (continued). "Per1/2−/− mice also exhibited a more robust immune response and slower tumor growth rate, indicating that the circadian clock also influences the immune response to melanoma tumors." (PMID 29581861, 2018). "On day 0, when tumor sizes were an average of 200 mm3 (~10 days post-injection), both wild-type and Per1/2−/− mice were subdivided randomly into three treatment groups: saline, cisplatin treatment at ZT0 (morning), or cisplatin treatment at ZT12 (evening)." (PMID 29581861, 2018). "Immunological data showed a significantly higher presence of CD4+ and CD8+ T cells in circulation and infiltration to tumor sites in the Per1/2−/− mice." (PMID 29581861, 2018). "Nevertheless, these results indicate that cisplatin was more effective at reducing tumor growth rate in the Per1/2−/− mice in a dose-dependent manner." (PMID 29581861, 2018). "Our research prompts that the role of PER1 on tumor occurrence and progression is not only exerted by regulating downstream CCGs, but also by simultaneously modulating the expression of many other clock genes in the clock gene network." (PMID 27602964, 2016). "Our findings prompt that the effect of PER1 on tumor occurrence and progression is not only achieved by regulating downstream CCGs, but also through the synergistic modulation of other clock genes in the network." (PMID 27602964, 2016). "We discovered that after PER1 knockdown, apoptosis was decreased and cell proliferation and in vivo tumor formation were enhanced." (PMID 27602964, 2016). "The tumor weights in the PER1-shRNA-I and Control-shRNA groups were, respectively, (0.55±0.13) g and (0.27±0.05) g." (PMID 27602964, 2016). "Further, PER1 is able to regulate numerous downstream cell cycle genes and cancer-related genes that act as CCGs, thereby it has a close relationship with tumor occurrence and progression." (PMID 27602964, 2016). "In BALB/c nu/nu nude mice subcutaneously injected with SCC15 cells, PER1 knockdown in the cells enhanced tumor development, leading to increased tumor weights and volumes." (PMID 26943040, 2016). "The tumor volumes in the PER1-shRNA-I and Control-shRNA groups were, respectively, (0.24±0.10) cm3 and (0.07±0.03) cm3." (PMID 27602964, 2016). "At the same time, PER1 knockdown enhanced tumor cell growth, proliferation, apoptosis resistance, invasion and metastasis in vitro and tumorigenesis in vivo." (PMID 26943040, 2016). "We also determined that apoptosis was decreased and cell proliferation and tumor formation were enhanced after PER1 knockdown in vitro and in vivo." (PMID 27602964, 2016). "Overexpression of Period1(Per1) and Period2(Per2) sensitizes human cancer cells to DNA damage-induced apoptosis, significantly increasing apoptosis in tumor cells." (PMID 25760074, 2015). "PER1 mRNA expression, MI and tumor weight had significant differences among the 4 time groups, which PI all confirmed to circadian rhythms." (PMID 23405233, 2013). "Recently, Per1 has been identified as a candidate tumor suppressor, epigenetically silenced in nonsmall-cell lung cancer (NSCLC)." (PMID 20353609, 2010). "PER1 seems to function as a tumour suppressor by regulating cell cycle genes and interacting with key DNA damage-activated checkpoint proteins." (PMID 20353609, 2010). "The levels of Per1 exhibit circadian patterns of gene expression in both tumor and normal tissues." (PMID 40495887, 2025). "In tumors, PER1 exerts tumor-suppressive effects and its low expression links to poor prognosis." (PMID 41451215, 2025). "CK1 and CK2 inhibitors are potential candidates for averting the degradation of PER1/2, which might be effective in potentiating the anti-tumor activities of period (PER) proteins in the case of GBM." (PMID 40495887, 2025). "We next used MCP-counter, a method of inferring immune cell populations from bulk tumor RNAseq, to determine whether cohorts expressing high or low levels of PER1 mRNA or PER1 protein had altered abundance of any immune cell types." (PMID 40715535, 2025).
tumor (continued). "CK1 and CK2 inhibitors are potential candidates for averting the degradation of PER1/2, which might be effective in potentiating the anti-tumor activities of the period (PER) proteins in the case of GBM." (PMID 40495887, 2025). "In tumors, PER1 has tumor-suppressive effects, with low expression correlating to poor prognosis." (PMID 41451215, 2025). "Collectively, these findings indicate that tumor cells might show abnormal oscillations in Per1 expression, which can eventually affect tumor survival and cell proliferation." (PMID 40495887, 2025). "Core circadian clock genes include the likely tumor suppressors PER1 and PER2 (53, –55)." (PMID 38319971, 2024). "Also, tumor growth can be suppressed and apoptosis can also be induced by overexpression of PER1 in cell lines." (PMID 38892035, 2024). "When cells from the same dataset were stratified based on cellular type, CLOCK and PER3 were preferentially expressed in tumour and stomal cells, PER1 was selectively expressed in immune cells and stromal cells but not in cancer cells, and TEF was selectively expressed in CAF subtypes." (PMID 39201344, 2024). "Similar to that observed for PER1, PER2 expression was associated with effectiveness in radiotherapy, again supporting the hypothesis that both genes are tumor suppressors." (PMID 34361055, 2021). "Regarding the negative elements of the clock machinery, Per2 genetic disruption accelerates tumor formation in different mouse models and overexpression of Per1 and Per2 genes sensitizes human cancer cells to apoptosis-mediated cell death induced by DNA damage." (PMID 34361055, 2021). "Then, we analyzed the expression levels of PER1 in different tumor types using the TIMER database." (PMID 34220965, 2021). "This study showed that PER1 decreased the sensitivity of tumor cells to chemotherapy-induced apoptosis, both in vitro and in xenograft mice model (in vivo), suggesting the detailed understanding of the association between the circadian clock protein/gene and tumor regulatory proteins/gene." (PMID 34959290, 2021). "Conversely, a reduced tumor growth-suppressing effect was observed in PER1-overexpressing tumors." (PMID 33804124, 2021). "Besides, PER1 and CLOCK were reported as potential biomarkers for head and neck squamous cell carcinoma, whereas PER2 was reported to be associated with vital tumor-related genes in oral cancer." (PMID 34745328, 2021). "PER1 was upregulated in three tumor types and downregulated in 24 types." (PMID 34220965, 2021). "In PC, overexpression of the clock gene PER1 promoted tumor cell apoptosis." (PMID 34966582, 2021). "Male STAD patients and patients with high tumor-grade had low PER1 expression." (PMID 34162762, 2021). "Together, these results suggest that T cells do not mediate stromal Per1–/–Per2–/–-associated tumor inhibition." (PMID 33123539, 2020). "PER1 is characterized as a circadian clock protein tumor suppressor." (PMID 32631453, 2020). "Employing different orthotopic tumor models, we showed that loss of stromal Per2, but not Per1, inhibits tumorigenesis and metastasis." (PMID 33123539, 2020). "Using orthotopic injection of cancer cells into clock-deficient mice, we find that stromal Per2, but not Per1, is required for tumor growth and metastatic colonization." (PMID 33123539, 2020). "Since low expressions of Per1 and Per2 were correlated with poorer tumor cell differentiation, deeper invasion depth and worse metastasis, it was reasonable to suppose that low expression of Per1 and Per2 might result in poorer OS, as studies pointed out." (PMID 32437452, 2020).
tumor (continued). "Downregulation of Per2 is correlated with increased levels of Cyclin D and Cyclin E and accelerated tumor growth in vivo whereas induced overexpression of either Per1 or Per2 has been shown to inhibit the growth of cancer cells and increase their apoptotic rate." (PMID 31409384, 2019). "Per1 negatively affects the growth of tumor cell and per2 functions as tumor repressor." (PMID 29607311, 2018). "Per1 and Per2 have tumor suppression activity, which may tie in with the anti-cancer mechanism under CR." (PMID 28768896, 2017). "Our findings clarify the tumor suppressor role played by PER1 during carcinogenesis." (PMID 26943040, 2016). "Three weeks after subcutaneous injection of untreated SCC15 cells or cells expressing PER1-shRNA-I into the backs of 10 nude mice, the tumor weights (volumes) in the PER1-shRNA-I and SCC15 groups were respectively 0.48±0.04g (0.28±0.09 cm3) and 0.19±0.07 g (0.10±0.08 cm3) (P<0.05)." (PMID 26943040, 2016). "In addition, we determined that apoptosis was decreased, whereas cell proliferation and tumor formation were enhanced, after PER1 knockdown in vitro and in vivo." (PMID 27602964, 2016). "This implies that PER1 protein acts as an important tumor suppressor." (PMID 26943040, 2016). "In this study, PER1 was presented as a candidate tumor suppressor in lung cancer." (PMID 26253128, 2015). "However, the expression level, function and circadian rhythm of PER1 altered greatly in different tumor types." (PMID 23405233, 2013). "Peak value of PER1 mRNA expression and trough values of MI, PI and tumor weight all appeared in middle activity phase, whereas trough value of PER1 mRNA expression and peak values of MI, PI and tumor weight all occurred in middle rest phase." (PMID 23405233, 2013). "Both Per1 and Per2 have been described as tumor suppressor genes." (PMID 21566258, 2011). "Thus, PER1 can function as a tumour suppressor by activating multiple pathways, including the DNA damage response." (PMID 20353609, 2010). "Similarly, significantly decreased expression levels of Per1 as compared to paired non-tumour tissues, have been reported in endometrial carcinoma (EC)." (PMID 20353609, 2010). "The loss of PER1 may influence OSCC progression via the AKT/mTOR signaling pathway, while PER1 modulates cell proliferation through glycolysis regulation and the PI3K/AKT pathway, positioning it as a tumor suppressor." (PMID 40243466, 2025). "Importantly, PER1 has cancer-relevant roles in cell cycle and DNA damage response which suggests it may have tumor intrinsic roles in modulating the response to anti-cancer therapeutics." (PMID 40715535, 2025). "The functional experiments presented here are focused on the tumor intrinsic role of LKB1 on PER1 mRNA and PER1 protein expression but do not test how loss of LKB1 affects the expression of additional core clock components nor the effect on the oscillation of clock-controlled genes in the lung." (PMID 40715535, 2025). "In addition, PER1, as one of the critical genes involved in tumor cell resistance to apoptosis, may also partially receive and amplify oncogenic signals from POLB." (PMID 38245510, 2024). "First, although we verified the expression of PER1 based on data from multiple public databases, further experiments are needed to clarify the molecular mechanism and mode of action by which PER1 regulates tumor-infiltrating cells and thereby affects the prognosis of OV patients." (PMID 34220965, 2021). "However, the biological functions and mechanism of PER1 in promoting tumor progression remain largely unknown." (PMID 33723221, 2021).
tumor (continued). "Consequently, PER1 could variably modulate the resistance of tumor cells against chemotherapy or radiation therapy." (PMID 33804124, 2021). "In addition, it was found that ALKBH5 could prevent tumor progression by regulating the posttranscriptional activation of PER1." (PMID 35046996, 2021). "Period1 (PER1), a core circadian gene, not only modulates circadian rhythm but may also play an important role in other biological processes, including pathways involved in the proliferation and apoptosis of tumor cells." (PMID 31350984, 2019). "However, the expression and function of PER1 differed greatly in various tumor types." (PMID 23405233, 2013). "Moreover, the circadian rhythm of PER1 expression varied greatly in different tumor types." (PMID 23405233, 2013). "In trastuzumab-resistant GC, metformin suppresses HK2-dependent glycolysis by inhibiting period circadian regulator 1 (PER1)-mediated circadian regulation of HK2, thereby restoring trastuzumab sensitivity and inhibiting tumor growth." (PMID 41171531, 2026). "Moreover, PER1 may modulate immune pathways through NK cell clocks, and its role in regulating the cell cycle and DNA damage repair underscores its potential as a tumor suppressor, making it a valuable target for cancer treatment." (PMID 40243466, 2025). "Furthermore, the G allele may influence MT2 expression in breast tissues, leading to changes in the central circadian clock and peripheral oscillators, including the appearance of the clock genes period 1 (Per1) and period 2 (Per2), which are acknowledged as tumor suppressor genes." (PMID 40736027, 2025). "For example, some studies have shown that PER1 and PER2 are significantly downregulated in OSCC and that their overexpression can inhibit glycolysis and tumor cell proliferation, thus inhibiting tumor growth." (PMID 36566175, 2022). "For instance, PER1 and PER2 proteins have already been described as tumor suppressors in cancer cell cultures, as well in animal experiments." (PMID 35897788, 2022). "Whereas the reduced sensitivity of cancer cells to chemotherapeutics induced by PER1 is detrimental because it compromises treatment efficacy, this effect might instead confer protection from toxic side effects of cytotoxic treatments in non-tumor cells with an intact circadian clock." (PMID 33804124, 2021). "PER1 can promote cell apoptosis and expression of TNF-α, IL-6, and programmed death 1 (PD-1)/PD-L1, and inhibit tumor invasion and TUBB2B gene expression." (PMID 34220965, 2021). "The loss of ALKBH5 post-transcriptionally decreased the expression of PER1 in YTHDF2-dependent manner, and facilitated cell migration, invasion, proliferation and tumor growth in pancreatic cancer." (PMID 33593354, 2021). "In tumor-bearing mice, the expression levels of five CCMCCs, including NR1D1, PER1, PER2, ARNTL, and DBP, were downregulated in hepatic metastasis from colorectal cancer when compared with healthy tissue." (PMID 34966582, 2021). "FBXL3 mediated degradation of CRY1 and CRY2 can re-activate the CLOCK-BMAL1 complex and increase the protein levels of period circadian protein homolog 1 (PER1) and 2 (PER2), two circadian clock regulators with tumor suppressor activity." (PMID 32226545, 2020). "In cancer cells, both PER1 and PER2 were shown to act as tumor suppressors and mutations in these genes were associated with human cancer." (PMID 33123539, 2020).
tumor (continued). "Accordingly, the aberrant expression of clock core genes such as CRY1, PER1, and PER2 has been shown to impact tumor progression in colorectal, prostate, and breast cancers, respectively." (PMID 29946530, 2018). "Similar functions have been observed in human studies, where PER1 and PER2 in normal cells promote apoptosis and act as tumor suppressor genes." (PMID 29958276, 2018). "Several clock genes showed a down-regulation when compared to their own neighbouring mucosa, i.e. PER1, PER2 and PER3, while CRY2 was down-regulated in both tumour and neighbouring tissue when compared to normal mucosa from unrelated donors." (PMID 27465361, 2016). "We found that PER1 knockdown not only increased MMP2 and MMP9 expression, but also decreased TIMP-2 expression, presumably leading to the observed increases in tumor cell migration and invasion." (PMID 26943040, 2016). "Among the clock genes, the expression of PER1, PER2, PER3 and CRY2 were significantly elevated in the benign tissue compared to the tumour tissue (p = 0.001, 0.002, 0.037 and 0.001 respectively)." (PMID 27465361, 2016). "In contrast, PER1 and CRY1 were up-regulated in tumour and neighbouring mucosa compared to the normal donor tissue." (PMID 27465361, 2016). "We also found that PER1 expression, MI, PI of BSCC cells and tumor weight all confirmed to circadian rhythms." (PMID 23405233, 2013). "Circadian variations of relative PER1 and MMP-2 mRNA expression, tumor growth and proliferation of tumor bearing mice of 4 time groups." (PMID 23405233, 2013). "PER1 expression was the maximum while MMP-2 expression MI, PI of tumor cells and tumor weight were the minimum at 16 HALO; while at 10 HALO PER1 expression was the minimum but MMP-2 expression MI, PI of tumor cells and tumor weight were the maximum." (PMID 23405233, 2013). "Our study, for the first time, demonstrated that PER1 and MMP-2 expression, MI of BSCC cells and tumor weight had significant differences among 4 time groups." (PMID 23405233, 2013). "A recent genomic methylation analysis of 12 ER+ and 12 ER− tumors identified 5 loci that are consistently hypermethylated in one or the other tumor type (MANEAL, PER1, NAV1, FAM124B, and ST6GALNAC1)." (PMID 21364760, 2011). "One potential explanation for this could be that the peak expression of PER1-driven anti-apoptotic genes in tumor cells also occurs at ZT13, resulting in increased tumor survival and development at this specific time point." (PMID 38245510, 2024). "Additionally, PER1 expression negatively correlates to GPX4 expression, suggesting that under hypoxic conditions, reduced PER1 levels in tumor tissues activate GPX4, leading to resistance against ferroptosis." (PMID 38612455, 2024). "The expression of PER1, AKAP12 and MMP17 was located in the cytoplasm of tumor cells." (PMID 37434173, 2023). "Besides, the overlapping genes that exhibited similar expression levels in tumor samples from both the TCGA and ICGC databases were shown in a Venn diagram, including DBP, NPAS2, PER1, RORA, and TIMELESS." (PMID 34745328, 2021). "We previously found that the expression of PER1 in OSCC tissue was remarkably decreased and was significantly correlated with Tumor, Node, Metastasis clinical stage and that the 5-year survival rate of patients with low expression of PER1 was significantly reduced." (PMID 33723221, 2021). "Here we show that selective loss of the core clock genes Per1 and Per2 in the TME not only does not promote cancer but actually inhibits tumor growth and metastatic colonization." (PMID 33123539, 2020).